STAT3 (signal transducer and activator of transcription 3)
Diseases named in the same sentence as STAT3 in open-access papers (continued):
Sharing a sentence is not in itself a finding about the gene and the disease.
ovarian carcinoma (continued). "This is followed by our in vivo-based investigation revealing for the first time the effects of minocycline to reduce both plasma and tumoral IL-6 expression along with down-regulation of tumoral p-STAT3, p-ERK1/2 and MCL-1 in an experimental model of ovarian cancer in mice." (PMID 23593315, 2013). "Since we observed that DIM can suppress IL-6-induced activation of STAT3 in ovarian cancer cells, we hypothesized that DIM mediated inhibition of STAT3 is in fact by inhibition of IL-6." (PMID 22280969, 2012). "Our results demonstrate that DIM suppresses the growth of ovarian cancer cells and potentiates the effect of cisplatin in vitro and in vivo by targeting STAT3 signaling without being toxic to normal ovarian cells." (PMID 22280969, 2012). "They found that curcumin failed to inhibit the phosphorylation of STAT3 at Ser727 in endometrial and ovarian cancer cells." (PMID 22662257, 2012). "In the light of the evidence supporting the activated status of STAT3 in ovarian carcinomas and the role of STAT3 in cell motility and EMT, this study sought to directly examine the role of this pathway in EGF-induced EMT in ovarian cancer cells." (PMID 19088723, 2009). "It has been proposed that constitutive STAT3 activation can result from aberrant EGFR signalling and a significant correlation between high overall levels of P-STAT3 expression and overexpression of EGFR and HER-2/neu has been reported in ovarian cancer specimens." (PMID 19088723, 2009). "Many synthetic compounds that inhibit phosphorylated STAT3 and EGFR tyrosine kinase activity have been shown to be effective in preclinical studies and in clinical trials of advance stages of non-small cell lung cancer, breast, and ovarian cancer." (PMID 18302761, 2008). "In this review we pointed out that ovarian cancer tumor cells may (over)express immunoregulatory molecules such as ligand "Letal", CD40 and Stat-3 which stimulate immune response." (PMID 16164749, 2005). "Annexin A3, P-glycoprotein (P-gp), signal transducer and activator of transcription 3 (STAT3), FAS, DNA methyltransferase-I (DNMT-1), multidrug resistance protein 2 (MRP2), ATP 7A, and ATP 7B are exosomal proteins that promote drug resistance in ovarian cancer cells." (PMID 38796525, 2024). "In addition, the pro-inflammatory cytokine IL-17A promotes the expression of STAT3 mediating fatty acids binding protein 4 (FABP4), which acts synergistically with fatty acid receptor CD36 to initiate the uptake of fatty acids to fuel ovarian cancer growth." (PMID 38245798, 2024). "Furthermore, in a study conducted by Yang and colleagues, glutamine, but not glucose, was found to regulate the STAT3-dependent invasive potential of ovarian cancer cells." (PMID 36834778, 2023). "In addition, the overexpression of CXCL8 in ovarian cancer cells activates mitogen-activated protein kinase (MAPK) signaling and signal transducer activator of transcription 3 (STAT3), which in turn increases the expression of VEGF and decreases the level of thrombospondin-1 (TSP-1)." (PMID 37762405, 2023). "Subsequent analysis showed increased levels of IL-6 in ovarian cancer patient ascites, and treatment using anti-IL-6 antibodies showed decreased invasion and migration, decreased mesenchymal phenotype, and decreased activation of the JAK/STAT3 downstream signalling." (PMID 36429126, 2022). "Similarly, activated SRC is found in 36% of primary ovarian cancers, and inhibiting SRC can reduce tumor growth, suggesting that in addition to blocking DNA damage repair, targeting both STAT3 and SRC in tumor cells can be an advantage of Niraparib over Olaparib." (PMID 36324587, 2022). "Indeed, STAT3 and Akt/β-catenin pathways have been shown to play an important role in driving the enrichment of breast CSCs, and β-catenin has been demonstrated to mediate the effect of KIT on promoting stemness of ovarian cancer." (PMID 34718356, 2022).
ovarian carcinoma (continued). "Unexpectedly, we found that Niraparib inhibited STAT3 phosphorylation, shown as a reduction in pSTAT3(Y-705) following treatment with Niraparib in both MIA PaCa-2 and PANC-1 human PDAC cell lines and OVCAR8 and PEO1 ovarian cancer cells, despite reduced PARylation by Niraparib." (PMID 36324587, 2022). "In that context, chemotherapy treatment of ovarian cancer cells in which TIMP-2 was knocked down failed to activate Stat3, implying that TIMP-2 and Stat3 may be critical regulators of chemoresistance." (PMID 35047406, 2021). "Therefore, miR-146b might improve the antitumour activity of ovarian cancer therapy by blocking both the EGFR and STAT3 pathways." (PMID 34369236, 2021). "However, we also demonstrated that EGFR knockdown could increase STAT3 phosphorylation in HO8910 and OVCAR-3 ovarian cancer cells." (PMID 34369236, 2021). "In the present study, we found that STAT3/p-STAT3 expression was significantly different in patients with serous vs. non-serous, endometrioid vs. non-endometrioid, and clear cell vs. non-clear cell ovarian cancer subtypes." (PMID 34789292, 2021). "Therefore, it will also be interesting to investigate whether DDP affects the activity of the transcription factor STAT3 and regulates the STAT3/DRP1 axis in DDP-resistant ovarian cancer cells." (PMID 35003356, 2021). "Furthermore, genistein inhibited the increased M2 polarization of macrophages and stemness of ovarian cancer SKOV3 and OVCA-3R cell lines by the co-culture of macrophages with ovarian cancer stem-like cells through disrupting the interleukin (IL)-8/STAT3 signaling axis." (PMID 32059369, 2020). "For instance, melittin can inhibit cell growth of human ovarian cancer cells increasing the expression of death receptors (DR3, DR4 and DR6) and the inactivation of the signal transducers and activators of the transcription 3 (STAT3) pathway, ending in the apoptosis of the cells." (PMID 33142794, 2020). "ID1, STAT3, and ATF6 may be targeted in combination with chemotherapy for ovarian cancer treatment." (PMID 32080166, 2020). "Moreover, the inhibition of STAT3 activity and Twist1 transcription could suppress EMT and inhibit tumor progression and chemoresistance in ovarian cancer and renal cancer cells." (PMID 32872659, 2020). "The numerous observations that both CD44 and STAT3 are critically involved in the VEGF pathway and tumor angiogenesis indicate that dual targeting of both factors could be a promising therapeutic target to improve antiangiogenic treatment in ovarian cancer." (PMID 33335857, 2020). "Interestingly, STAT3 signaling has not been studied in ovarian cancer in the context of immune evasion." (PMID 32444701, 2020). "Inhibition of STAT3 signaling reduces IL-4, IL-6, and TNF-α production with a significant increase in anti-inflammatory IL-10 levels, creating an imbalance between Treg/Th17 cells, thus establishing the immunosuppressive microenvironment which promotes ovarian cancer progression." (PMID 32992449, 2020). "To test the combined effect of these inhibitors on cell signaling pathways in ovarian cancer cells, we treated SKOV3 cells with sunitinib and dasatinib, alone or in combination, for 24 h, then measured the expression of the phosphorylated and total forms of STAT3, SRC, AKT, and MAPK by Western blot." (PMID 32927828, 2020). "Although several reasonable ways of targeting pStat3 function and several targeted inhibitors have been reported, the role of Stat3 in the pathogenesis of ovarian cancer has not been fully elucidated, and so far, no small molecular inhibitor of Stat3 has been prepared for clinical development." (PMID 31778258, 2020). "However, only STAT1 but not STAT3 siRNA knockdown impeded IL-27-induced PD-L1 protein expression, consistent with previous reports examining T cells and ovarian cancers." (PMID 31730010, 2019).
ovarian carcinoma (continued). "IL-6-induced STAT3 phosphorylation levels were found to be increased in cells treated with follicle-stimulating hormone (FSH), luteinizing hormone (LH), 17β-estradiol or estrogen and it facilitated cell proliferation in human ovarian surface epithelial (HOSE) and ovarian cancer (OVCA) cell lines." (PMID 31861720, 2019). "Also, using a per-patient z-score transformation, we did not observe a significantly increased amount of phospho-STAT3 in the ovarian cancer cohort compared to other TCGA diseases." (PMID 31534498, 2019). "All of these results demonstrate that Jagged1 can crosstalk with the JAK/STAT3 pathway, and they all cooperate to promote the aberrant occurrence of EMT, further reinforcing the abilities of invasion and migration of platinum‐resistant ovarian cancer in vivo and in vitro." (PMID 30993885, 2019). "This study investigated whether inhibition of the Janus kinase 2 (JAK2)-signal transducer and activator of transcription 3 (STAT3) pathway by momelotinib is sufficient in suppressing tumor burden and prolonging the disease-free survival period in a mouse model of ovarian cancer." (PMID 29682172, 2018). "Given the significant roles of STAT3 and PTEN, and the close interaction of miR-216a with both of them, miR-216a is an important molecule in cancer and further investigations are warranted to further demonstrated the clinical utility of miR-216a in ovarian cancer." (PMID 30061175, 2018). "In this study, we described the inhibitory effects of CT on cell proliferation and glycolysis in ovarian cancer cells through suppressing STAT3/SIRT3 signaling pathway, which indicates that CT may be developed to be a potential drug for the treatment and prevention of ovarian cancer." (PMID 30094960, 2018). "In this study, our results, for the first time, demonstrate that feedback activation of STAT3 might explain in part why gefitinib is not effective against human ovarian cancer." (PMID 25928246, 2015). "Additionally, to rule out the non-specific cytotoxicity of Stattic, A2780 ovarian cancer cells and HUVECs were treated with 20 μM Stattic, which had little STAT3 phosphorylation recognized." (PMID 25261365, 2014). "To address whether or not inhibition of STAT3 induces apoptosis in ovarian cancer cells, we silenced STAT3 using shRNA in SKOV-3 cells." (PMID 22280969, 2012). "We now show that the activation of JAK2/STAT3 may be a pre-requisite for EGF-induced EMT in these ovarian cancer cell lines, as pharmacological inhibition of JAK2 in ovarian cancer cells not only led to an inhibition of STAT3 activation but also inhibition of EGF-induced EMT phenotypes." (PMID 19088723, 2009). "The downregulation of HDC expression led to the activation of the IL-6/STAT3/S100A9 pathway, stimulating Th17 cells to secrete IL-17A, thereby promoting ovarian cancer progression, which suggests that HDC may be a potential therapeutic target for the comorbidity of ovarian cancer and depression." (PMID 39720595, 2024). "With the advances of both A2B inhibitors (TT‐4, TT‐702, GS‐6201, PBF‐1129, etc.)and STAT3 inhibitors (C188‐9, Napabucasin, GLG‐801, WP‐1066, PCUR‐101, etc.)in the clinic, combination of those drugs with PARP inhibitors may achieve better therapeutic outcomes in ovarian cancers." (PMID 37278400, 2023).
ovarian carcinoma (continued). "Moreover, a lower expression level of PIK3R1 induced by YTHDC1 knockdown leads to activation of STAT3 signaling, which further promotes GANAB expression in the nucleus, followed by an increase of GANAB-mediated N-glycan biosynthesis in ovarian cancer cells, which promotes ovarian cancer progression." (PMID 37781028, 2023). "In addition to its suppressive activity against CD8+ T cells in ovarian cancer TME, previous studies have demonstrated that MDSC increase the stem cell-like properties of ovarian cancer cells via by producing PGE2, inducing the microRNA101 or CSF2/STAT3 pathway activation." (PMID 33562495, 2021). "GSNO attenuates STAT3 and Akt phosphorylation induced by growth factor and reduces the basal level of their phosphorylation forms, suggesting that GSNO may inhibit cell proliferation by regulating the growth factor-induced signaling pathway in ovarian cancer cells." (PMID 34356634, 2021). "A natural product, apigenin, reduced AXL expression in ovarian cancer cell lines without affecting IL6 production and STAT3 phosphorylation, suggesting the selectivity of the STAT proteins in the regulation of AXL expression." (PMID 36835239, 2023). "To date, there are no available data showing the impact of direct STAT3 inhibitors on SNAIL 1 and SNAIL 2 expression and/or the induction of EMT in various ovarian cancer cell lines." (PMID 33478150, 2021). "Treatment with sunitinib alone inhibited activation of STAT3 in SKOV3 cells, which has not been demonstrated previously in ovarian cancer cells." (PMID 32927828, 2020). "In the context of ovarian carcinoma, there are no reports analyzing CD44 or STAT3 signaling within CAFs themselves." (PMID 33335857, 2020). "IL-6/STAT3 and PIK3CA inhibition did not reverse platinum chemoresistance in ovarian cancer and IL-6 levels cannot be considered as a marker of sensitivity to platinum-based chemotherapy." (PMID 29930760, 2018). "High expression of STAT1, STAT3, STAT4, and STAT6 mRNA were correlated to a better OS in grade III ovarian cancer patients, but not in grade I or II ovarian cancer patients." (PMID 28536310, 2017). "Although the role of EMT in regulating metastasis in ovarian cancer cells is still not clear, overexpression of EGFR and constitutively active STAT3 have been shown in clinical specimens and ovarian cancer cell lines." (PMID 19088723, 2009). "Also, expression of p-STAT3 and p-STAT5 but not p-STAT1 and p-STAT6, were significantly higher in ovarian cancer cells compared to benign and normal tissues." (PMID 34358244, 2021). "Furthermore, STAT3 proved to be the most essential and universal factor determining the expression of SNAIL 1 and SNAIL 2 in ovarian cancer cells, regardless of their resistance to cisplatin or place of origin." (PMID 33478150, 2021). "Hence, combination therapies that include JAK2/STAT3 and CSC-specific targeted agents and a non-CSC-targeted agent such as chemotherapy, may be a more effective approach for the treatment of ovarian cancer." (PMID 29682172, 2018). "In human ovarian cancer SKOV3 cells and the chemoresistant ovarian cancer SKOV3/TR cells, apigenin significantly decreased Axl and Tyro3 receptor tyrosine kinase at both RNA and protein levels, without changing the IL-6 production and phospho-STAT3 protein levels." (PMID 29034071, 2017).
colon carcinoma (549 papers, 2007 to 2026). "We evaluated the efficacy of TTI-101 in the AOM-DSS mouse model of colitis-associated CRC and found that TTI-101 markedly reduced colon tumor burden, at least in part, by normalizing the STAT3-driven pro-oncogenic transcriptome in colonic mucosa." (PMID 41226842, 2025). "Previous studies have demonstrated that the inhibition of STAT3 activity directly impacts the levels of anti-apoptotic molecules and renders colon tumor cells susceptible to 5-FU treatment." (PMID 40149862, 2025). "In summary, our results suggest that CEBPB facilitates the progression of UCCRC by activating the NF-κB/STAT3 signaling cascade, thereby contributing to a better understanding of the mechanisms underlying the progression from colitis to colon cancer." (PMID 40487290, 2025). "FEZF1-AS1 expression has been associated with poor survival and tumor metastasis in colon cancer, and it activates STAT3 signaling." (PMID 38609520, 2024). "It speeds up the development of colon cancer caused by an infection by turning on the STAT3 signaling pathway." (PMID 39394128, 2024). "They revealed that Luteolin inhibited the growth, migration, and invasion potential of SW620 and SW480 colon cancer cells caused by M1 polarization by acting on the interleukin-6 (IL-6)/signal transducer and activator of transcription 3 (STAT3) pathway." (PMID 36992138, 2023). "For this reason, the deletion of the hotspot mutation region in the DNA-binding domain of STAT3induced colon cancer cell growth and progression due to genome-wide changes in the transcription of STAT3-target genes." (PMID 36982677, 2023). "The expression and phosphorylation of JAK2 and STAT3 in the tumor tissues were detected by Western blotting to investigate the mechanisms underlying FTGs-mediated inhibition of colon tumor growth." (PMID 38202610, 2023). "For instance, cancer cell invasion is associated with increased STAT3 activation, and STAT3 activation decreases E-cadherin in colon cancers." (PMID 37846594, 2023). "In inflammation-associated colon cancer, S1P was crucial for the production of the NFκB-dependent cytokine IL-6, essential for STAT3 activation." (PMID 36672428, 2023). "The possible participation of STAT3 and STAT5 in colon cancer has been highlighted, and STAT3 and STAT5 have been associated with colon cancer survival." (PMID 35468892, 2022). "STAT3, a pleiotropic transcription factor, is an essential mediator of epithelial repair and inflammatory processes in colitis and colitis-associated colon cancer." (PMID 35832050, 2022). "Inhibition of STAT3 or IL-6 greatly reduces the tumor burden in inflammation-associated colon cancer." (PMID 35664068, 2022). "Many studies revealed the association between STAT3 activation, up-regulated expression of Cyclin D1, c-Myc, and survivin, and cell cycle progression in colon cancers." (PMID 35056682, 2022). "Aberrant activation of JAK2/STAT3 signaling is frequently presented in colon tumors and implicated in the tumor vasculature reprogramming." (PMID 33976735, 2021). "Persistent activation of STAT3 signaling is frequently detected in human colon cancers, and in association with invasion, survival, and growth of colorectal cancer cells." (PMID 34900688, 2021). "Taken together, our data demonstrates that deletion of the hotspot mutation region in the DNA-binding domain of STAT3 reduces colon cancer cell growth and progression because of genome-wide changes in the transcription of STAT3-target genes." (PMID 33535185, 2021). "Stathmin is prometastatic in colon cancer, a process that requires pS38Stathmin and knockdown of Stathmin was shown to reduce STAT3, confirming an association of these two proteins." (PMID 32797246, 2021). "It has been shown that anti-inflammatory transcription factor Stat3 in macrophages enhances the risk of invasive adenocarcinoma in colon cancer." (PMID 34804993, 2021).